IL10 (interleukin 10)
Diseases named in the same sentence as IL10 in open-access papers (continued):
Sharing a sentence is not in itself a finding about the gene and the disease.
cancer (continued). "The combination of IL10 and anti-PDL1 also showed good responses in other cancer patients." (PMID 32802517, 2020). "Moreover, after receiving cancer treatment radioactivity in lung cells diminished and cancer promoting factors declined (VEGFR2, ICAM-1, bFGF, KC, TNF-α, IL-6, IL-12, IL-10 and IL-13) showing a diminution of metastatic competency of the exosomes." (PMID 32570802, 2020). "Altogether, IL-10 serves as an immunosuppressive agent, with effects on many cell types in the TME, that could serve as a therapeutic target in cancer therapy." (PMID 31681327, 2019). "Of these, the average expression of the two genes, including CD70 and PDCD1, and the 12 isoforms derived from the seven genes, including CD40, CD70, IL6, IL10, STAT1, STAT6, and TNFRSF14, were cancer immunotherapy-related genes (false discovery rate (FDR) < 0.01)." (PMID 31292525, 2019). "Considering the reports describing IL-10 upregulation in LSCC and its potential role in EMT induction in cancer, we next hypothesized that the cytokine could, in the context of EMT induction in LSCC, be of importance." (PMID 31885577, 2019). "Because cytokine secretion by CAR-T cells targeting cancer cells indicates the activation and specific cytotoxicity of T cells, we analyzed the levels of the classic cytokines, TNF-α, IL-10, INF-γ, and IL-2, to assess the cytokine profile when CAR-T cells were incubated with U-251MG cells." (PMID 31288857, 2019). "IL-10 and TGF-β play an equally important role during cancer development." (PMID 31134056, 2019). "However, the levels of pro-tumor cytokines, namely IL-10 and MCP-1, were obviously higher when cells with downregulated Hsp70 contacted monocytes for all three carcinoma cell pairs." (PMID 31861801, 2019). "Cancer cells can activate some immunosuppressive cells such as regulatory dendritic cells (DCs), and regulatory T cells (Tregs) through production of many immunosuppressive molecules such as transforming growth factor (TGF)-β, interleukin (IL)-10." (PMID 29435196, 2018). "Interestingly, we also show that seven major gene regulators (TP73, RICTOR, NUPR1, NKX2‐3, MYCN, IL10, and EPO) involved in inflammation, oxidative stress, DNA damage, and cancer processes were affected by MP radiation." (PMID 29786969, 2018). "The suppression of anti-cancer immunity by TGF-β and IL-10 has been reported in several studies." (PMID 29439673, 2018). "In contrast, as lesions progressed to cancer, the pro-inflammatory phenotype subsided and was replaced with the inhibitory mediator IL-10 and with Treg cells in wildtype mice, although not in IL-23R KO mice." (PMID 29664967, 2018). "Besides, IL-10 and TGF-β1 are also produced by other cell types, such as macrophages and some cancer cells." (PMID 29967800, 2018). "Other immune signatures of cancer immune status, namely PD-1, PD-L1, CTLA4, T cell immunoglobulin and mucin domain 3 (Tim3), IDO and IL-10, that potentially could be used as biomarkers of NACT response were analyzed in the pre-treatment biopsies." (PMID 30555458, 2018). "Furthermore, cancer cell lines- exposed human monocytes demonstrated a significant induction of TGF-β, PGE2 and IL-10 as compared to unexposed cells." (PMID 29668679, 2018). "Macrophages and some cancer cells can produce TGF-β1 and IL-10." (PMID 29967800, 2018). "Although the present study gives important new insights into the potential crosstalk between NOD1, IL-10-induced STAT1-STAT3 signalling and SOCS protein functions in haematopoietic cells, potential relationships amongst these proteins in the context of cancer need to be further investigated." (PMID 28432285, 2017). "Although previous studies have suggested that IL-10 plays an important role in cachexia from different cancer types, our model promoted no changes in IL-10 plasma levels." (PMID 29033844, 2017). "We showed that pro-inflammatory and anti-inflammatory cytokines IFNγ, TNFα, and IL-10 did not induce expression of B7x on human or murine cancer cells." (PMID 29137299, 2017).
cancer (continued). "The presence of a specific TGFβR inhibitor was able to inhibit the conversion to IL-10 production by irradiated cancer cells; however, the TGFβR inhibitor was not able to restore TNFα production by macrophages." (PMID 27602953, 2016). "The increase in IL-10 secretion in LICRC patients was further confirmed by measuring IL-10 secretion in the whole CD4+ T cell population, thus confirming the immunosuppressive milieu in cancer patients." (PMID 26885615, 2016). "In colorectal carcinogenesis, IL-10 promotes cancer growth, rather than inhibition, through its immunosuppressive activity." (PMID 26905729, 2016). "There were significantly more IL-10+ cells in OSCC than in OLK and OLP tissues (P < 0.001), suggesting that IL-10 may contribute to immunosuppression in the cancer microenvironment." (PMID 28053372, 2016). "Results from these two large randomized aerobic exercise intervention trials suggest that aerobic exercise does not alter IL‐10 or IL‐4 in a manner consistent with chronic disease and cancer prevention." (PMID 27485297, 2016). "BAL cytokines were generally independent of the presence of cancer although BAL IL-10 was lower in cancer septic mice." (PMID 27018973, 2016). "Because IL-10 is preferentially produced by activated HMDMs, and most cancer cell lines secrete no or low concentrations of IL-10, IL-10 production is useful to evaluate HMDM activation." (PMID 27404320, 2016). "When activated with IL-2, NK92 cells were found to have no/low cytotoxicity against NK sensitive cancer stem cells; however, they retained the ability to secrete high levels of regulatory cytokines IL-6 and IL-10 with no or slight secretion of IFN-γ and TNF-α." (PMID 26247631, 2015). "As controls, 10 ng/ml LPS or 10 ng/ml IL-10 alone were added to invasion assays in the absence of macrophages, having no influence on the number of invasive cancer cells (data not shown)." (PMID 26043921, 2015). "The suppression of M2-induced IL-10, IL-12, and TNF-α secretion was observed during the transition from inflammatory hyperplasia to carcinoma, but these cytokines were again expressed at high levels during metastasis, which was concordant with the mRNA expression data." (PMID 25434400, 2015). "We found that p38i (SB203580) was still able to enhance IL-12 and suppress IL-10 in advanced cancer patients (p = 0.0015 for IL-12, p = 0.0025 for IL-10) without affecting other cytokines (not shown)." (PMID 23901045, 2014). "Increased plasma IL-10 levels were detected in the patients with LSCC (P<0.01) and vocal leukoplakia (P<0.01), while the level of plasma IL-10 was found to increase with the cancer staging." (PMID 24765208, 2014). "To examine whether the expression of the immunosuppressive cytokines IL-10 and TGF-β corresponded with the Foxp3+ expressing cancer cells we stratified in two different groups according to the percentages of expression in the immunohistochemical analysis." (PMID 23382847, 2013). "No other studies on IL10 polymorphisms and dietary fibre, meat, cereals, or fish intake, smoking status or NSAID use in relation to CRC or any other cancer were found." (PMID 22594912, 2012). "Thus, we inspected the gene expression levels of the examined genes (CD4, CD25, FOXP3, TGF-β, IFN-γ, IL-10, CTLA-4, PD-1, PD-L1, ARG1) in the CRC patients and confirmed they were all upregulated in the cancer patients." (PMID 22496728, 2012). "It is necessary to develop an adjuvant that does not promote IL-10 and T reg function in vivo for the future establishment of an anti-cancer vaccine." (PMID 21533081, 2011). "TMV secreted by cancer cells can convert CD4(+)CD25(–) T cells into CD4(+)CD25(+)FOXP3(+) Treg, while increasing the expression by these cells of immune-suppressive factors, such as FasL, IL-10, TGF-β1, CTLA-4, granzyme B, and perforin." (PMID 22046194, 2011). "Carcinomas of the IL-10−/− /celecoxib model did not exhibit signs of genomic instability in our study." (PMID 21799775, 2011).
cancer (continued). "Other immune regulatory factors have been found elevated, i.e. IL-10, which have been described as negative indicator for survival of patients with different types of cancers." (PMID 20214814, 2010). "As the cancer progressed at the tongue root, the percentage of CD3+CD4+ T lymphocytes and NK cells and the levels of IFN-γ and IL-2 decreased gradually, while the percentage of CD3+CD8+ T lymphocytes and the levels of IL-4 and IL-10 increased." (PMID 17338814, 2007). "Furthermore, the levels of multiple cytokines, including IL-2, IL-4, IL-6, IL-10, TNF, and IFN-γ in the supernatant of the OHSV2-DSTEFAP5/CD3 group co-cultured with cancer cells and fibroblasts, showed a significant increase compared to groups with either cell type alone." (PMID 40406146, 2025). "CD4+ Th cells assist in activating CD8+ CTLs and also produce cytokines that indirectly contribute to the anti-cancer immune response, common pro-inflammatory cytokines include IL-1, IL-6, IL-8, and tumor necrosis factor-α (TNF-α), while common anti-inflammatory cytokines include IL-4 and IL-10." (PMID 40881864, 2025). "CAF-derived cytokines, such as IL-6, IL-10, could activate the JAK/STAT pathways in cancer cells." (PMID 40517166, 2025). "These IgA PCs secrete IL-10 and express immunomodulatory receptors such as PD-L1 and FAS-L, thereby further inhibiting cytolytic activity.These results suggest that cytokine therapies have great potential to modulate B-cell responses and shape the TME to improve cancer treatment outcomes." (PMID 41285707, 2025). "Furthermore, hormone-receptor negative tumors, higher-grade tumors, and locally advanced cancer are more prevalent in TNBC patients with IL-10 expression in their malignancies." (PMID 40933989, 2025). "Yet, no IL-10 inhibitor has reached clinical use for cancer." (PMID 41007766, 2025). "In cancer patients, exercise training did not significantly affect IL-10 levels." (PMID 40219022, 2025). "Like other cytotoxic cancer therapies, immunotherapy promotes inflammation within the TME, which can include cytokine release syndrome characterized by hypersecretion of pro-inflammatory cytokines, including IL-6, IL-1, TNFα, IL-5, IL-10, IFN, and TGFs by various immune cells." (PMID 38330013, 2024). "Other contributing factors include dendritic cells (DCs), interleukin-10 (IL-10), transforming growth factor-β (TGF-β), regulatory T cells (Tregs), and reduced CD8+ T cell priming and infiltration, all leading to immune evasion and decreased cancer immunosurveillance." (PMID 39337605, 2024). "Interestingly, we also found that IL6Rα expression was negatively correlated with pSTAT3 response to IL-10, indicating that heightened IL6Rα and IL-6 in cancer patients may be dominating STAT3 signaling and in turn suppressing the IL-10 responsiveness." (PMID 39389979, 2024). "The immunostimulatory functions of the PEGylated form of IL-10 (pegilodecakin), that extend the cytokine lifetime, were confirmed in cancer patients, but it did not improve the outcome of patients with gemcitabine-refractory metastatic pancreatic or metastatic lung cancer." (PMID 39204319, 2024). "Recently, it has been shown that anti-inflammatory cytokines (IL-10 and IL-4) are protective against CIPN; however, systemic use of IL-10 in general has had poor clinical outcomes as it can promote the progression of cancer and propagate chronic viral infections." (PMID 38330029, 2024). "Yet, IL-10 is not universally detrimental in cancer contexts." (PMID 39132165, 2024). "Indeed, we discovered that 23-HBA decreased the phosphorylation level of STAT6 protein in M2 macrophages, accompanied by a decrease in M2-related cytokine IL-10 secretion and an inhibition of STAT3/Bcl-2 signaling of cancer cells, resulting in a reduction in 5-FU resistance." (PMID 38554148, 2024).
cancer (continued). "PA-MSHA has demonstrated positive anti-cancer effects across various cancer types by interacting with the immune system in several ways: it induces M1 polarization of macrophages, Th1 immune response promotion, and increases the secretion of IFN-γ while reducing the production of IL-10 and IL-4." (PMID 38339275, 2024). "However, the immunosuppressive function of IL10+ IgD- CD38+ Bregs could be blocked, and cancer immunotherapy enhanced, by using PPARδ inhibitors." (PMID 38826800, 2024). "In the context of cancer, Tregs are recruited to the TME, where they suppress effector T cells and other immune cells through mechanisms such as secreting immunosuppressive cytokines (e.g., IL-10, TGF-β), expressing immune checkpoint molecules (e.g., CTLA-4, PD-1), and altering metabolic pathways." (PMID 39594765, 2024). "Several possible mechanisms are involved in cancer progression, such as Tregs inhibiting T lymphocytes’ function, NK cells, DCs, and macrophages, or weakening the immune response by secreting immunosuppressive cytokines such as TGF-β and interleukin-10 (IL-10)." (PMID 36675580, 2023). "In accordance with the reported immunosuppressive effect of cancer cells on macrophages in the TME, incubation of the RAW 264.7 macrophages in ID8 CM resulted in increased production of the immunosuppressive cytokine IL-10 and decreased production of the M1 phenotype-related chemokine CXCL10." (PMID 37376134, 2023). "IL-10 trended to decrease in Omicron-infected cancer patients and Omicron-infected non-cancer-afflicted subjects at the early stage, and its increase in non-cancer-afflicted subjects was higher than that in cancer patients at the late stage." (PMID 37035158, 2023). "Functionally, M2-type macrophages release immunosuppression factors such as IL-10, transforming growth factor (TGF)-β, and arginase 1, to exert immune effects and release stem cell inducers, such as IL-8, IL-10, IGF, TGF-β1, and pleiotrophin, to maintain cancer stemness." (PMID 37187454, 2023). "As the expression and function of sICAM-1 in cancer has been well characterized, which further supports the pro-migration ability of SEMA4A in the pathological progression of PCa, more attention is paid on the biological activity of IL-10, as well as its relation with SEMA4A." (PMID 37779872, 2023). "In addition, there is a complicated interaction effect between IL-10 and the MAPK pathway, whereby the activation of the MAPK pathway, which increases the production of IL-10 and TGF by cancer cells by maturing immune suppressive regulatory CD4+ T-cells, results in a complex interaction effect." (PMID 36339551, 2022). "Cancer-derived miR-214, for instance, can promote the proliferation of CD4+ CD25 high Forkhead Box P3 (FoxP3) + Regulatory T cells (Tregs) by addressing PTEN and stimulating IL-10 production, resulting in host immune repression and accelerated tumor progression." (PMID 36793341, 2022). "Interventions that activate this CD8+ T cell/TIM3/IL-13-to-macrophage/IL-10 pathway to boost endogenous pain resolution could provide a treatment for persistent CIPN, thereby improving quality of life of the growing number of cancer survivors." (PMID 35260535, 2022). "Moreover, IL10 released by MSDCs and TAMs favors a CD4+ Th2 response with B-cell engagement over CD4+Th1 and cytotoxic CD8+T (Tc1) responses, which are both effective cancer immunosurveillance mechanisms." (PMID 35392957, 2022). "In addition, select immune mediators and cancer biomarkers also exhibited high importance scores in our analyses for predictions of LD and vaginal pH (MIF), as well as genital inflammation (IL-6, IL-10, MIP-1α), further confirming the link between vaginal microbiota and host immune responses." (PMID 35196323, 2022).
cancer (continued). "Thus, we comprehensively measured representative inflammatory mediators, including IL-1β, IL-6, IL-10, IL-12p70, TNF, PGE2, and VEGF concentrations in the saliva of patients with cancer, which is convenient to measure, less invasive to collect, and can be done repeatedly." (PMID 35476641, 2022). "The anti-cancer activity was assessed in histological preparations of breast organs, CD4+/CD8+ T cells from spleen organs, and several essential cytokines involved in breast cancer, such as IL-1, IL-6, TNF-α, IFN-γ, TGF-β, and IL-10, in the blood serum of mice." (PMID 35765486, 2022). "In addition, the regulatory cytokines, including IL-10 and TGF-β, could be secreted by Tregs to sustain the immunosuppressive microenvironment to assist cancer cells during immune escape." (PMID 35432381, 2022). "When cancer forms, IL-10 may mainly stimulate NK- and CTL-mediated killing of cancer cells." (PMID 36009467, 2022). "In the present study, we detected increased levels of IL-10 and TGF-β in response to HKTB stimulation of TEMs, although it remains unclear whether both anti-inflammatory cytokines were secreted by the macrophages or cancer cells due to our co-culture system." (PMID 35477732, 2022). "Their results suggest that surgical and metabolic response to an IA justify the adoption of an entirely laparoscopic approach performing a right colectomy for cancer, but the role of other inflammatory mediators, such as IL-1β, IL-10, IL-13, TNFα and insulin, was not considered." (PMID 33958669, 2021). "Although IL-10 and TGF-β can induce a shifting of macrophages towards the alternative activated immunosuppressive M2 state, a clear correlation between their secretion by KRAS mutated cancer and macrophage polarization has not been established." (PMID 33777798, 2021). "Interestingly, we found that ER-positive MCF-7 cancer cells unlike MDA-MB-231 did not respond with a decline in IFN-gamma or IL-10 production in lymphocytes." (PMID 34440813, 2021). "Although Breg cells have been identified in various human cancers, including breast cancer, we could not clearly define Breg cell populations by IL-10 expression." (PMID 33846305, 2021). "In addition, OSCAR expression was positively correlated with infiltrating levels of TAMs in 20/20 types of cancer, especially BRCA (CCL2, r=0.428; CD68, r=0.769; IL10, r=0.542), COAD (CCL2, r=0.561; CD68, r=0.624; IL10, r=0.536), and THCA (CCL2, r=0.612; CD68, r=0.870; IL10, r=0.597)." (PMID 34093786, 2021). "Furthermore, Grenald found that inhibition of S1PR1 could reduce cancer-induced bone pain (CIBP) and promote the expression of IL-10 in lumbar spinal cord, suggesting that S1PR1 is involved in the regulation of CIBP and neuroinflammation." (PMID 33029266, 2020). "Although IL-10 levels were higher in the late VAE group than in the non-VAE group on day 1 and day 7, whether cancer patients were at risk of developing VAE for this reason needs further investigation." (PMID 32728165, 2020). "These suggest that MET could contribute to the conservation of IL-10 expression levels when MO comes into contact with cancer cells, without inducing changes usually seen after interplay with cancer cells." (PMID 33108409, 2020). "In addition to our data, these results suggest that MerTK could hinder immunogenic cancer cell death response by inhibiting TLR pathways directly, and indirectly by inducing production of immunosuppressive cytokines such as IL-10." (PMID 33101282, 2020). "At nine weeks, momordicoside G treatment resulted in not only mild lung tissue injury but also slight carcinoma lesions which were in line with the decreased M1-like macrophages (iNOS+ cells) and NLRP3 inflammasome and the increased levels of alveolar IL-10 and TGF-β1." (PMID 30984004, 2019). "Furthermore, the IL-23R KO mice lacked the increases in Treg and IL-10 levels that were seen in wildtype mice as lesions advanced to cancer." (PMID 29664967, 2018).